KIF18A (kinesin family member 18A)
Diseases named in the same sentence as KIF18A in open-access papers (continued):
Sharing a sentence is not in itself a finding about the gene and the disease.
tumor (continued). "This suggests that increases or decreases in microtubule dynamics may compromise spindle integrity in CIN tumor cells, an idea supported by observations that multipolar spindles form in cells with dampened microtubule dynamics due to KIF18A overexpression." (PMID 33619254, 2021). "Thus, KIF18A represents a potential target for exploiting vulnerabilities specific to a significant fraction of tumor cells displaying CIN or aneuploidy." (PMID 33619254, 2021). "KIF18A levels were found to be significantly related to clinicopathologic factors associated with alpha-fetoprotein (AFP) concentrations (≥200 ng/mL), tumor size (≥5 cm), clinical tumor-node-metastasis (TNM) stage, and portal vein tumor thrombus (PVTT)." (PMID 31392101, 2019). "This suggests that the expression of KIF18A can promote tumour formation in vivo." (PMID 29466986, 2018). "Some researchers have successfully modified the expression of KIF18A in other tumours." (PMID 29466986, 2018). "Besides high KIF18A expression, size of tumor ≥5cm, multiple tumor number, III-IV of TNM stage, the AFP value (≥200 ng/ml), recurrence together with PVTT and distant metastasis were associated with a shorter DFS and OS." (PMID 25431949, 2014). "However, the mechanistic basis for why a subset of CIN tumor cells depend on KIF18A remains unclear." (PMID 42039568, 2026). "Thus, trapping KIF18A in a microtubule-bound state may be an effective inhibition strategy for specifically reducing the proliferation of CIN tumor cells." (PMID 38410188, 2024). "Therefore, it is speculated that KIF18A may accelerate tumor cell division by interfering with the cell cycle, resulting in the formation of tumors." (PMID 36830695, 2023). "Furthermore, KIF18A expression was positively correlated with many common immune checkpoints, including PD-L1, PD-1, CTLA4, TIGIT, HAVCR2, PDCD1LG2, and LAG3, indicating that KIF18A may be a new target for tumor immunotherapy." (PMID 36830695, 2023). "Thus, KIF18A may be an effective target to specifically inhibit the growth of CIN tumor cells, while inducing relatively low toxicity in somatic, diploid cells." (PMID 33619254, 2021). "Furthermore, analyses found regulatory correlations between members, with KIF10 regulated by KIF18A, which indicates a putative deficiency in singling out any KIFs to analyze alone rather than balancing the interplay between tumor-related KIFs." (PMID 32322170, 2020). "Evidence is emerging that over expression of KIF4A and KIF18A may play roles in tumor progression." (PMID 24327603, 2013). "CIN+ tumor cells specifically require KIF18A for proliferation, and KIF18A inhibition in CIN+ tumor cells show mitotic delays, multipolar spindles, and cell apoptosis." (PMID 40175357, 2025). "Furthermore, chemical inhibition of KIF18A specifically decreased the proliferation of chromosomally unstable cell lines but did not affect the growth of diploid cells, highlighting the therapeutic potential of KIF18A inhibitors for specifically targeting tumor cells." (PMID 38410188, 2024). "To further examine the in vivo activity of our KIF18A inhibitors, we evaluated the OVCAR-8 CDX tumor model." (PMID 38151625, 2024). "The expression level of KIF18A in LGG tissues was higher, which was positively correlated with the size of the tumor and the proliferation ability of the tumor cells." (PMID 37759912, 2023). "While near-diploid tumor cells exhibited relatively minor mitotic delays upon KIF18A knockdown (KD), CIN tumor cells frequently experienced prolonged delays with large subpopulations of cells failing to complete mitosis altogether." (PMID 34135330, 2021). "Following KIF18A inhibition, CIN tumor cells exhibit mitotic delays, multipolar spindles, and increased cell death." (PMID 33619254, 2021).
tumor (continued). "All 6 KIFs selected by LASSO regression were seen overexpressed in tumor samples comparing to normal samples (KIF10, KIF15, KIF18B, KIF4A: P < 0.0001; KIF18A: P = 0.0003; KIF20A: P = 0.0022), which in accordance with bioinformatics results." (PMID 32322170, 2020). "In tumor tissues, CCNB2, DYNC1LI1, SPC25 and KIF18A expressions were mainly detected in the cytoplasm, and KIF11 expression was detected mainly in the cytoplasm and nucleus." (PMID 33111935, 2020). "The KIF18A expression level had positive relevance to the alpha-fetoprotein (AFP) (≥200 ng/ml), tumor size (≥5cm), clinical tumor-node-metastasis (TNM) stage and portal vein tumor thrombus (PVTT) in HCC (all P <0.05)." (PMID 25431949, 2014). "The results showed that size of tumor >5 cm (HR, 3.119; 95% CI, 1.795-5.421; P <0.001), III-IV of TNM stage (HR, 1.650; 95% CI, 1.076-2.529; P=0.022) and high KIF18A expression (HR, 1.602; 95% CI, 1.029-2.579; P =0.031) were independent predictors for DFS." (PMID 25431949, 2014). "Other six factors (size of tumor >5 cm, multiple tumor number, III-IV of TNM stage, PVTT, distant metastasis and high KIF18A expression) were analyzed with the stepwise multivariate Cox proportional hazard model for both DFS and OS." (PMID 25431949, 2014). "KIF18A-mediated HCC promotion might be correlated with several abnormally activated signaling pathways, including the Akt/MMP7/9 axis to stimulate tumor invasion and migration, and the CyclinB1-related axis to promote proliferation." (PMID 38433242, 2024). "The loss of one particular protein, KIF18A, was associated with significantly decreased viability in CIN tumor cells but not their stable, near-diploid counterparts." (PMID 34135330, 2021). "Centrosome fragmentation in KIF18A KD CIN tumor cells did not require bipolar spindles, however, and was observed even in cells with monopolar spindles." (PMID 34135330, 2021). "After silencing KIF18A in SMMC-7721 and HepG2 cells, cell growth was obviously inhibited; the migration and invasion abilities were significantly decreased and the in vivo tumour weight was decreased compared to the control group (0.201 ± 0.088 g vs 0.476 ± 0.126 g, p = 0.009)." (PMID 29466986, 2018). "Independent functional studies have shown that KIF18A depletion impairs proliferation, migration, and invasion; increases apoptosis; induces cell cycle arrest in the A549 and H1975 LUAD models; and also inhibits tumour growth and metastasis in in vivo tumour models." (PMID 40002279, 2025). "Furthermore, through analysis of gene expression levels in tumor and normal samples and survival analysis, CXCL8, KIF18A, and E2F1 showed high expression and poor prognosis, which indicated that they may play a role in promoting ESCA progression." (PMID 32851080, 2020). "Size of tumor >5 cm (HR, 2.614; 95% CI, 1.495-4.568; P=0.001), III-IV of TNM stage (HR, 1.895; 95% CI, 1.235-2.907; P=0.003), recurrence (HR, 2.074; 95% CI, 1.374-3.131; P =0.001) and high KIF18A expression (HR, 1.682; 95% CI, 1.089-2.600; P =0.019) were independent predictors for OS." (PMID 25431949, 2014). "Taken together, the diploid cells tested here did not require KIF18A to proliferate, while the majority of CIN tumor cells displayed a dependence on KIF18A for efficient growth and survival." (PMID 33619254, 2021).
infection (4 papers, 2016 to 2025). The state of being infected such as from the introduction of a foreign agent such as serum, vaccine, antigenic substance or organism. "KIF18A expression increased following infection with IAV, which led us to investigate its effect on IAV replication." (PMID 32253833, 2020). "In this study, we found that the inhibition of KIF18A disrupted the infection‐induced activation of signalling pathways, including AKT, p38 and SAPK that are necessary for viral replication." (PMID 32253833, 2020). "Although further investigation for the efficacy of the treatment with KIF18A inhibitor at later times post‐infection in vivo is required, inhibition of KIF18A would be an efficient therapeutic strategy for the treatment of IAV infection." (PMID 32253833, 2020). "After infection (as monitored by M1 expression), KIF18A expression increased in all three cell lines." (PMID 32253833, 2020). "In addition, Kif11, along with kinesins Kif18a and Kif25, were in proximity to L2 during infection." (PMID 39629998, 2025). "We repeated this PLA analysis with kinesins Kif18a and Kif25, since previously published data suggest that HPV requires these kinesins during infection." (PMID 39629998, 2025).
adenocarcinoma (1 paper, 2020). A common cancer characterized by the presence of malignant glandular cells. "The expression of the Kif18A protein was higher in highly differentiated tumors than in poorly/moderately differentiated tumors (adenocarcinoma: P = 0.032; SCC: P = .022)." (PMID 31977917, 2020). "The expression of the Kif18A protein was higher in stage III NSCLC than in stage I+II NSCLC (adenocarcinoma: P = .029; SCC: P = .022)." (PMID 31977917, 2020). "The expression of the Kif18A protein was higher in adenocarcinoma and SCC tissues than in the corresponding paracancerous normal tissues." (PMID 31977917, 2020).
lung (1 paper, 2020). "The expression of the Kif18A protein in lung SCC was significantly higher than in the corresponding paracancerous normal tissues (P = .005)." (PMID 31977917, 2020).
KIF18A also shares sentences with these, for which no sentence is quoted: gastric cancer (5 papers); renal cell carcinoma (2); Serous Ovarian Cancer (2); asbestosis (1); bladder cancer (1); clear cell renal carcinoma (1); Fanconi anemia (1); head and neck squamous cell carcinoma (1); infectious disease (1); liver cirrhosis (1); malaria (1); mantle cell lymphoma (1); metastatic disease (1); metastatic prostate carcinoma (1); neuroblastoma (1); oligoastrocytoma (1); oligodendroglioma (1); Pan (1); pancreatic cancer (1); rectum cancer (1); small cell lung carcinoma (1); testicular germ cell tumours (1).